NME3 (NME/NM23 nucleoside diphosphate kinase 3)
Description:
Catalyzes the transfer of a gamma-phosphoryl group from a nucleoside triphosphate, mainly ATP, to a nucleoside diphosphate via a ping-pong mechanism involving a phosphohistidine intermediate, therefore contributing to the nucleoside triphosphate homeostasis. In vitro, can also use other phosphate donors such as UTP and GTP. Independently of its nucleoside diphosphate kinase activity, involved in mitochondrial membrane tethering, a prerequisite for fusion through direct membrane-binding and hexamerization. Involved in DNA repair of both single- and double-stranded breaks by associating with the ribonucleotide reductase (RNR) complex via interaction with the histone acetyltransferase KAT5, facilitating recruitment to DNA damage sites independently of its kinase activity. Inhibits granulocyte differentiation. May be required for ciliary function during renal development (By similarity).
Synonyms: NDPK-C; NDK3; DR-nm23; NM23-H3; NDPKC; NM23H3; c371H6.2
Tractability: Small molecule: a structure with a bound ligand is known; it has a binding pocket of medium quality. Antibody: UniProt places it where antibodies can reach, with high confidence. PROTAC: ubiquitination databases record sites on it; its protein half-life has been measured.
Gene: Protein-coding gene on chromosome 16 (1,770,317 to 1,771,732, reverse strand). Ensembl gene ENSG00000103024.
Subcellular location: Mitochondrion outer membrane; Cytoplasm; Cytoplasm, cytoskeleton, cilium basal body
Pathways (Reactome):
Metabolism: Interconversion of nucleotide di- and triphosphates
Gene Ontology:
Molecular function: ADP binding; cAMP binding; GDP binding; mitochondrion-mitochondrion outer membrane tether activity; nucleoside diphosphate kinase activity; phosphatidic acid binding; protein binding
Biological process: DNA repair; dTTP biosynthetic process; mitochondrial fusion; mitochondrial outer membrane fusion; nucleoside triphosphate biosynthetic process; protein hexamerization; apoptotic process; CTP biosynthetic process; GTP biosynthetic process; nucleobase-containing small molecule metabolic process; UTP biosynthetic process
Cellular component: cytoplasm; mitochondrial outer membrane; mitochondrion; ciliary basal body; cytosol
Genetic constraint (gnomAD): Loss-of-function variants: 26 observed, 14.07 expected, observed/expected ratio (o/e) 1.85, 90% interval 1.29 to 1.97. The synonymous counts are far from expectation, so gnomAD's model fits this gene poorly and the ratio says little. Missense variants: 323 observed, 202.55 expected, observed/expected ratio (o/e) 1.59, 90% interval 1.46 to 1.75. Synonymous variants: 140 observed, 82.02 expected, observed/expected ratio (o/e) 1.71, 90% interval 1.49 to 1.93.
Homologues: Orthologues: chimpanzee NME3 (100% identical), pig NME3 (96% identical), rat Nme3 (91% identical), mouse Nme3 (89% identical), macaque NME3 (75% identical), zebrafish nme3 (73% identical), tropical clawed frog nme3 (67% identical), guinea pig NME3 (63% identical). Paralogues in human: NME1 (59% identical), NME2 (56% identical), NME4 (53% identical), NME6 (30% identical), NME8 (28% identical), NME5 (28% identical), NME7 (27% identical), NME9 (15% identical).
Diseases named in the same sentence as NME3 in open-access papers:
NME3 is named in the same sentence as 23 diseases in open-access papers, as found by Europe PMC text mining. Sharing a sentence is not in itself a finding about the gene and the disease. The quoted sentences say what the papers report.
ciliopathies (3 papers, 2018 to 2021). "Depletion of NME3 resulted in renal malformations and left–right patterning defects typical of ciliopathies in Xenopus along with a loss of cilia in complementary vertebrate and cell culture models." (PMID 31417417, 2019). "The ciliopathy-typical manifestations of NME3 depletion in two vertebrate in vivo models, the biochemical association of NME3 with validated NPHPs, and its localization to the basal body reveal a role for NME3 in ciliary function." (PMID 30111592, 2018). "Depletion of nme3 in zebrafish and Xenopus resulted in typical ciliopathy-associated phenotypes, such as renal malformations and left-right asymmetry defects." (PMID 30111592, 2018). "We conclude that mutations in the NME3 gene may aggravate the ciliopathy phenotypes observed in humans." (PMID 30111592, 2018). "The association of NME3 with the ciliary nephronophthisis proteins NEK8, CEP164, and ANKS6 supports its role as a ciliopathy gene." (PMID 31417417, 2019). "In another example of patient driven gene discovery, identifying a role for the DNA repair protein NME3 in cilia established another example for a growing list of ciliopathies." (PMID 31417417, 2019). "To determine the relevance of NME3 as a potential novel ciliopathy gene, we performed targeted sequencing of all five coding exons and adjacent splice sites of NME3 (GenBankTM accession number NM_002513.2) in 768 individuals with NPH-related ciliopathies." (PMID 30111592, 2018). "Our data add NME3 and ANKS6 to the number of proteins linked to both ciliopathies and the DNA-damage response and thus strengthen substantially the notion that replication stress and the genomic instability of tubule cells may contribute to the pathogenesis of nephronophthisis." (PMID 30111592, 2018).
nephronophthisis (2 papers, 2018 to 2020). Progressive tubulointerstitial injury, inherited in an autosomal recessive pattern, caused by mutations in genes involved in ciliary function, which may result in an end stage renal failure. "Largely identified in nephronophthisis, mutations within DDR genes such as ZNF423, CEP164, NME3, and AATF are sufficient to cause disease via ciliary dysfunction." (PMID 32351541, 2020). "Hence, our data provide evidence that NME3 represents a potential nephronophthisis disease gene." (PMID 30111592, 2018).
neuroblastoma (2 papers, 2019 to 2020). Neuroblastoma (NB) is the most common solid, extracranial childhood tumor. "NME1, NME2, and NME3 were also each identified from the NME1 immunoprecipitated from neuroblastoma cells, which also supports the notion of hetero-oligomerization and the autophosphorylation of these family members." (PMID 32392889, 2020). "Furthermore, it has been established that the murine neuroblastoma cell line N1E-115 expressing Nme3 formed significantly fewer colonies in soft agar, while both Nme2-expressing NIH3T3 fibroblasts and Nme2-expressing HLK3 hepatocytes form colonies, unlike control cells that do not form any." (PMID 31877804, 2019).
Arrhythmia (1 paper, 2024). Any cardiac rhythm other than the normal sinus rhythm. "Eight of these associations were novel (LMNA, SMAD6, HSPB9, TMEM95, KLF1, TET2, NME3, KDM5B) and 5 genes have previously been linked to arrhythmias (SCN5A, TTN, RPL3L, PKP2, PMVK)." (PMID 38390584, 2024).
atrial fibrillation (1 paper, 2024). A disorder characterized by an electrocardiographic finding of a supraventricular arrhythmia characterized by the replacement of consistent P waves by rapid oscillations or fibrillatory waves that vary in size, shape and timing and are accompanied by an irregular ventricular response. "Atrial fibrillation was associated with rare variations in 8 genes (TTN, RPL3L, KLF1, TET2, NME3, KDM5B, PKP2, PMVK)." (PMID 38390584, 2024). "Atrial fibrillation (ICD10 code I48) was associated with rare variation in 8 genes (TTN, RPL3L, KLF1, TET2, NME3, KDM5B, PKP2, PMVK)." (PMID 38390584, 2024).
cyst (1 paper, 2018). A sac-like closed membranous structure that may be empty or contain fluid or amorphous material. "The specificity of the knockdown phenotype was confirmed by coinjection of the human NME3 mRNA, which rescued the frequency of cyst formation significantly." (PMID 30111592, 2018). "In addition, CRISPR-mediated indel formation in nme3 resulted in a significant rate of cyst formation." (PMID 30111592, 2018).
diabetic retinopathy (1 paper, 2025). "Notably, variants in genes such as nucleoside diphosphate kinase 3 (NME3), LOC728699, and fas-activated serine/threonine kinase (FASTK) have been associated with reduced susceptibility to diabetic retinopathy in certain populations." (PMID 41010507, 2025).
glioma (1 paper, 2025). A benign or malignant brain and spinal cord tumor that arises from glial cells (astrocytes, oligodendrocytes, ependymal cells). "In the Glioma/NC group, 8 proteins (COL1A1, PRL, VWF, HBD, SF3B1, NME3, RRBP1, and CSRP1) were selected, with an AUC of 0.892 in the training set and 0.871 in the validation set (accuracy: 78.5%)." (PMID 39716938, 2025).
lung carcinoma (1 paper, 2025). "Additionally, NME3, identified as a component of this pathway, enhances TLR5-mediated NFκB signaling in response to flagellin, thereby contributing to antitumor immunity in lung cancer patients." (PMID 40841456, 2025).
lymph node metastasis (1 paper, 2025). "ADSL, ADCY3, and NME6 were associated with lymph node metastasis, distant metastasis, and differentiation, whereas APRT and NME3 were independent of these clinical variables." (PMID 40017120, 2025).
polycystic kidneys (1 paper, 2018). "NME3 could provide the substrate for cilium-associated G-proteins such as RPGR (retinitis pigmentosa), GPR48 (polycystic kidneys), RanGDP/GTP, and ARL6 (retinitis pigmentosa and BBS)." (PMID 30111592, 2018).
tumor (5 papers, 2013 to 2025). "The second most differentially expressed gene, NME3, is associated with purine and pyrimidine metabolism as well as tumor metastasis." (PMID 24098497, 2013). "Given genome instability as a driver of tumor evolution, the correlation of low NME3 with poorer survival in a number of cancers is closely related to its function in mitochondrial regulation that controls redox to influence genome stability." (PMID 32708927, 2020). "Additionally, NME3 (Nucleoside Metabolism Enzymes 3) plays a significant role in repairing both single- and double-stranded breaks in DNA, contributing to genomic instability and promoting malignant tumor progression." (PMID 40283935, 2025). "Notably, NME3 emerged as an independent predictor of poor outcomes, capable of forecasting prognosis regardless of clinical variables that determine tumor aggressiveness." (PMID 40017120, 2025).
cancer (4 papers, 2010 to 2025). A tumor composed of atypical neoplastic, often pleomorphic cells that invade other tissues. "Given genome instability is a hallmark of cancer, we further studied the function of NME3 in genome stability." (PMID 32708927, 2020). "By analysis of a human cancer database, it has been shown that low expression of NME3 is correlated with poorer prognosis in a variety of cancers." (PMID 32708927, 2020).
NME3 also shares sentences with these, for which no sentence is quoted: breast carcinoma (3 papers); heart failure (2); chronic kidney disease (1); immune system disease (1); meningioma (1); metabolic disorder (1); nephrotic syndrome (1); Parkinson disease (1); retinitis pigmentosa (1); tuberculosis (1).